CRP (C-reactive protein)
Diseases named in the same sentence as CRP in open-access papers (continued):
Sharing a sentence is not in itself a finding about the gene and the disease.
delirium (continued). "Further, in the participants with the 90th percentile (24.46 mmol/L) of preoperative homocysteine, the association between postoperative plasma concentration of CRP and postoperative delirium incidence disappeared." (PMID 36212043, 2022). "In ICU patients, higher levels of CRP and procalcitonin are associated with a longer period of delirium or coma." (PMID 34526093, 2021). "Traditionally, during the high inflammatory period, a higher CRP level is associated with a higher risk of post-operative delirium." (PMID 34912245, 2021). "Recent studies have demonstrated associations between traditional inflammatory markers and delirium, such as C-reactive protein (CRP), interleukin (IL)-6, IL-8, IL-2, and tumor necrosis factor (TNF)." (PMID 34034650, 2021). "Other studies have shown that the increase of preoperative CRP and the decrease of preoperative total protein, albumin, and hemoglobin are independent risk factors for postoperative delirium, which contradicts our conclusions." (PMID 34901277, 2021). "As per studies, a higher occurrence of delirium in post-operative hip surgery patients is associated with higher concentrations of CRP and IL-6." (PMID 33415126, 2020). "An association was found between delirium, less coma-free days, elevated levels of CRP and procalcitonin, which implicated inflammation as a vital mechanism in delirium pathophysiology." (PMID 33415126, 2020). "In the subgroup analysis of patients under age 68, only preoperative EF, level of albumin, and C-reactive protein were associated with postoperative delirium by univariable analysis." (PMID 33189145, 2020). "In conclusion, our study suggests that elevated serum level of CRP alone is a risk factor for and predicts postoperative delirium in patients receiving cervical-lumbar surgeries." (PMID 32851079, 2020). "The two most common biomarkers in these six studies that reported a positive association with delirium were CRP (n=3) and IL-6 (n=3)." (PMID 32321448, 2020). "In the postoperatory period risk of Delirium was associated with levels of creatinine clearance (p=0.035) and C-reactive protein (CRP) (p=0.029)." (PMID 30890150, 2019). "So on the one hand, our findings are consistent with established theories such as the role of neurotransmitters, inflammation, and stress response in delirium (i.e., reported association of acetylcholine, IL-6, CRP, procalcitonin, and cortisol)." (PMID 31263968, 2019). "Other groups reported associations of delirium with high levels of Galectin-3 and CRP among women in postpartum intensive care units." (PMID 30405391, 2018). "Some studies suggest preoperative C-reactive protein as a risk factor for delirium but C-reactive protein was only higher in patients with delirium at postoperative period." (PMID 30515421, 2018). "We investigated the association between preoperative statin exposure and postoperative delirium and demonstrated that preoperative statin exposure was associated with a lower incidence of postoperative delirium and lower CRP levels." (PMID 29570715, 2018). "Inflammation and cholinergic blockade, as measured by serum CRP and PAA, respectively, were associated with delirium in critically ill patients, and serum CRP and PAA were correlated with each other." (PMID 27011789, 2016). "The association between high CRP levels and delirium was shown by several studies, and questioned by others." (PMID 26106326, 2015). "Immunotherapy with cytokines can induce delirium (IL-2, IFN) and increased systemic cytokines and acute phase proteins (IL-6, IL-8, CRP) are associated with delirium post hip fracture." (PMID 20471138, 2012). "C-reactive Protein (CRP) kinetics have also been examined in elderly patients with hip fractures, showing an association between elevated CRP levels and complications like infections and delirium." (PMID 40297586, 2025).
delirium (continued). "Given the high clinical relevance and accessibility of CRP testing, understanding its association with postoperative delirium may provide valuable prognostic insight." (PMID 41303282, 2025). "The authors hypothesized that elevated C-reactive protein levels in the perioperative and postoperative periods are associated with an increased risk and severity of postoperative delirium after cardiac and neurosurgical procedures." (PMID 41303282, 2025). "A previous study conducted on patients with advanced cancer admitted to palliative care units reported a significant association between a higher CRP level (≥10 mg/dL) and the occurrence of delirium, suggesting that patients with systemic inflammation tend to have restlessness due to delirium." (PMID 41302347, 2025). "Admission clinical parameters associated with delirium (all p<0·001 unless otherwise specified) included low cognitive score, clinical dehydration, abnormal white cell count, C-reactive protein concentration more than 6 mmol/L (p=0·0041), and pressure sore risk." (PMID 40754365, 2025). "Furthermore, differences in serum IL-8, IL-10, and CRP concentrations were associated with postoperative delirium." (PMID 39860413, 2025). "Multivariable stratified association between Hs-CRP and postoperative delirium." (PMID 39958614, 2025). "Routine monitoring of CRP in the early perioperative period may provide a simple and accessible tool for identifying patients at increased risk of delirium, allowing timely preventive and therapeutic interventions." (PMID 41303282, 2025). "The risk factors include advanced age, comorbidities, and systemic inflammation, defined by elevated biomarkers, such as the neutrophil-to-lymphocyte ratio (NLR) and C-reactive protein (CRP), which are associated with an increased postoperative delirium (POD) risk." (PMID 40572710, 2025). "Therefore, age ≥ 65 years, a known risk factor for delirium, was the only inclusion criterion in our study, along with a newly proposed criterion of CRP level > 25 mg/L." (PMID 41010627, 2025). "Additionally, age, frailty, and high CRP levels were all identified as risk factors for postoperative delirium." (PMID 38952533, 2024). "Similarly, age, dyspnea, delirium, abnormal bilateral chest x-ray, CRP, and sodium were risk factors for death." (PMID 39425809, 2024). "In addition, the acute phase reaction serum amyloid protein 1 (SAA1) and the C-reactive protein (CRP) seem to be implicated in the pathogenesis of SAD-delirium." (PMID 37958765, 2023). "C-reactive protein ≥20 mg/l and serum sodium <125 mM/l were associated with more severe delirium." (PMID 36856697, 2023). "Furthermore, some symptoms, such as dyspnea, delirium, or global deterioration, along with some analytical parameters, such as increased CRP or ferritin, were associated with increased mortality." (PMID 37892655, 2023). "Of the laboratory variables, there was an association between delirium and increased CRP values." (PMID 38100603, 2023). "C-reactive protein (CRP) is associated with postoperative delirium." (PMID 36212043, 2022). "It was hypothesized that preoperative plasma concentrations of homocysteine would modify the established association between postoperative plasma concentration of CRP and postoperative delirium in patients." (PMID 36212043, 2022). "Finally, one study showed that C-reactive protein (CRP) measured on ICU stay was associated with the development of delirium, as many aetiological factors associated with delirium will produce inflammation, which elevates CRP levels." (PMID 33546592, 2021). "Elevated serum CRP after surgery may be a risk factor for and a predictor of postoperative delirium." (PMID 32851079, 2020). "Moreover, preoperative CRP was examined to be a risk factor for postoperative delirium in a surgical setting." (PMID 32851079, 2020).
delirium (continued). "We hypothesize that changes in the white blood cells differential count, as well as the CRP concentration may show that post-cardiac surgery delirium is associated with inadequate immune system response." (PMID 31684066, 2019). "An association between high CRP levels and delirium was shown in several studies." (PMID 29641605, 2018). "The pooled data from continuous data showed that CRP levels were significantly associated with delirium (OR: 1.10, 95% CI: 1.01-1.20, p = 0.030); and the pooled data from categorical data revealed that high CRP levels increased the risk of delirium (OR: 2.66, 95% CI: 2.00-3.53, p < 0.001)." (PMID 41695631, 2026). "Furthermore, we investigated whether including delirium, frailty, and C-reactive protein (CRP) levels—risk factors for mortality that were unavailable at the time when the original index was developed—could enhance its predictive accuracy." (PMID 39841475, 2025). "However, the preoperative levels of homocysteine could modify the association between the postoperative levels of CRP and the incidence of delirium." (PMID 39839309, 2024). "Therefore, according to this hypothesis, CRP was proposed as a suitable marker to identify individuals at risk of delirium." (PMID 32244301, 2020). "Moreover, ROC curve analysis showed that the increment amplitude of CRP had a moderate predictive effect on the occurrence of postoperative delirium, which suggested that the increase in CRP after anesthesia and surgery was a risk factor for postoperative delirium occurrence." (PMID 32851079, 2020). "Besides, CRP may lead to the stimulation of the formation of reactive oxygen species (ROS) which result in blood brain barrier disruption, thereby causes delirium." (PMID 33415126, 2020). "Therefore, it is speculated that the increase in CRP may indirectly reflect the enhancement of central neuroinflammation and may be a risk factor for delirium requiring pending further investigation." (PMID 32851079, 2020). "In this pilot study, inflammation, as measured by high procalcitonin and CRP levels at admission, was associated with fewer days alive and free of acute brain dysfunction in critically ill patients, suggesting that inflammation plays an important role in delirium and coma in the ICU." (PMID 21366899, 2011). "CRP, for example, can incite the formation of reactive oxygen species, causing disruption of the blood brain barrier and resultant neuronal dysfunction, which may manifest as delirium." (PMID 21366899, 2011). "This study sought to investigate the association between the high-sensitivity C-reactive protein to lymphocyte ratio (hs-CLR) and the risk of postoperative delirium in elderly patients undergoing surgery for hip fractures." (PMID 41650049, 2026). "Laminectomy was associated with higher postoperative C-reactive protein (CRP) levels, which coincided with greater delirium intensity." (PMID 41303282, 2025). "Future large-scale, prospective, and multicenter studies using standardized delirium assessment tools are warranted to confirm the predictive value of CRP and to explore its integration into comprehensive perioperative risk stratification models." (PMID 41303282, 2025). "This retrospective study demonstrated that elevated C-reactive protein (CRP) levels are significantly associated with a higher incidence and severity of postoperative delirium in patients undergoing cardiac and neurosurgical procedures." (PMID 41303282, 2025). "A similar pattern was observed in the neurosurgical group, where patients with elevated CRP also demonstrated significantly higher delirium scores." (PMID 41303282, 2025). "C-reactive protein levels were significantly higher in the delirium group (median 0.4, IQR 0.0-5.5 mg/dL vs median 0.1, IQR 0.0-1.85 mg/dL; P=.03)." (PMID 39895101, 2025).
delirium (continued). "Although the current study demonstrated highly significant statistical associations between postoperative C-reactive protein (CRP) levels and delirium incidence, the analysis remains observational." (PMID 41303282, 2025). "On day 1, cardiac surgery patients with elevated CRP levels exhibited significantly higher delirium scores compared to those with normal CRP concentrations." (PMID 41303282, 2025). "First, its retrospective and single-center design limits the ability to establish causal relationships between C-reactive protein (CRP) levels and the development of postoperative delirium." (PMID 41303282, 2025). "Elevated CRP and IL-6 have been linked to BBB permeability and microglial activation, mechanisms implicated in delirium pathophysiology." (PMID 40889075, 2025). "The aim of this study was to assess the relationship between C-reactive protein (CRP) levels and the incidence of postoperative delirium in patients after cardiac and neurosurgical procedures hospitalized in the intensive care unit." (PMID 41303282, 2025). "Patients who developed delirium exhibited lower preoperative neutrophil counts, accompanied by a trend toward lower leukocyte and haemoglobin levels and higher creatinine and CRP." (PMID 41227085, 2025). "C-reactive protein (CRP) and pro-inflammatory cytokines such as IL-6 have been consistently linked to the occurrence and duration of delirium in critically ill and postoperative patients." (PMID 41459337, 2025). "Participants in cluster 3 presented clinically orthogonally to cluster 1 (lower baseline cognition, higher frailty, more delirium, higher CRP and lower albumin)." (PMID 41462244, 2025). "Multivariable logistic regression analysis of high-sensitivity C-reactive protein and postoperative delirium." (PMID 39958614, 2025). "Participants in cluster 2 were clinically mid-range for baseline cognition, premorbid frailty, yet high in acute illness measures (delirium and arousal deficit scores, high CRP, high likelihood of physiological derangement)." (PMID 41462244, 2025). "Although there exists some inconsistency about the role of CRP in delirium as a potential biomarker, it can be focused on future in-depth research to clarify its role broadly." (PMID 39700095, 2024). "Several studies have demonstrated a link between proinflammatory cytokines (C-reactive protein, interleukin-6, and tumor necrosis factor-alpha) and delirium." (PMID 39604840, 2024). "There is a growing body of evidence supporting a link between CRP levels and postoperative delirium in various settings." (PMID 38566241, 2024). "Current studies indicate a strong correlation between postoperative delirium and C-reactive protein (CRP), a protein that is produced in response to inflammation and tissue damage." (PMID 38902693, 2024). "In our study, cerebrovascular disease, fracture, CCI, APACHE II, MV, delirium, and CRP were significant in predicting functional impairment in critically ill patients, which is consistent with previous findings." (PMID 38789502, 2024). "Among the unique proteins, we focused on the top 13 most investigated proteins (IL-6, CRP, IL-8, S100B, IL-10, TNF-a, IL-1b, Cortisol, MCP-1, GFAP, IGF-1, IL-1ra, and NFL) that are significantly associated with delirium." (PMID 39700095, 2024). "The chance of an older adult with a CRP above the reference values used by the laboratory being diagnosed with delirium is 14% greater than that of an older adult with a normal CRP (below 0.5ng/dL)." (PMID 38100603, 2023). "This is supported by greater serum concentrations of CRP and IL-6 in patients who developed delirium during hospitalization." (PMID 37360340, 2023). "A meta-analysis of six studies revealed a correlation between CRP and delirium, but the results presented were highly heterogeneous (I2 = 72.92%)." (PMID 37649721, 2023).
delirium (continued). "Regarding hematological parameters, delirium patients have lower protein, albumin, hemoglobin, and potassium levels, but higher lactic acid, C-reactive protein (CRP), and creatinine levels." (PMID 37239615, 2023). "C-reactive protein (CRP), for example, isan appropriate marker of inflammation in patients with delirium particularly thoseundergoing surgery." (PMID 38774845, 2023). "Inflammatory mediators such as IL-1B, IL-6, IL-8, IL-10, TNF-alpha, and C-reactive protein (CRP), have all shown associations with delirium." (PMID 36803215, 2023). "A majority of the patients with delirium showed increased CRP levels (mean 50.58 mg/L, SD: 54.13 mg/L) and also elevated but still in range WBC levels (mean: 9.4 109/L, SD: 4.18 109/L)." (PMID 36928887, 2023). "Our systematic review identified nine studies that showed elevated CRP serum concentrations at hospital admission as a predictor of delirium." (PMID 37360340, 2023). "Preoperative homocysteine and postoperative CRP were evaluated in this study because postoperative CRP is an established blood biomarker of postoperative delirium." (PMID 36212043, 2022). "The value of CRP/Alb in the diagnosis of POD after surgery was significantly higher than that of CRP and Alb, providing an effective predictor for clinical prediction of postoperative delirium." (PMID 36051706, 2022). "The association between the postoperative plasma concentration of CRP and the incidence, duration, and severity of postoperative delirium can be modified by the apolipoprotein E (APOE) 4 genotype and the catechol-O-methyltransferase (COMT) genotype." (PMID 36212043, 2022). "However, it remains largely unknown whether the established association between the postoperative blood concentration of CRP (a precipitating factor) and postoperative delirium depends on preoperative predisposing factors such as preoperative blood homocysteine concentration." (PMID 36212043, 2022). "Proinflammatory proteins are highly sensitive while with low specificity for the diagnosis or prediction of delirium, including IL-1, IL-6, C-reactive protein (CRP), interleukin, procalcitonin (PCT), and TNFa." (PMID 35547218, 2022). "Of note, a statistically significant interaction was observed between preoperative plasma concentration of homocysteine and postoperative plasma concentration of CRP on the incidence of postoperative delirium (P = 0.044)." (PMID 36212043, 2022). "Patients with postoperative delirium had a higher plasma concentration of CRP from postoperative days 2–5." (PMID 36212043, 2022). "A previous study showed that the participants with plasma concentrations of CRP greater than 235.73 mg/mL on postoperative day two were 1.5 times more likely to develop postoperative delirium with more severe symptoms." (PMID 36212043, 2022). "In this study, the mean CRP of patients in the delirium group was 20.33 mg/L, which was about 2 times higher than the normal range." (PMID 36051706, 2022). "CRP/Alb as a predictor of perioperative delirium in elderly patients with TKA has certain rationality and feasibility." (PMID 36051706, 2022). "It has been reported that postoperative elevation of peripheral C-reactive protein (CRP) and interleukin 6 concentrations is associated with higher risks of postoperative delirium." (PMID 35294925, 2022). "Delirium is known to be closely related to neuroinflammation, which can be assessed by the increased neutrophil-to-lymphocyte ratio or C-reactive protein level." (PMID 36226079, 2022). "Patients with a history of delirium during ICU showed higher CRP value and lower renal function before discharge, but the CPX values at discharge were not significantly affected by delirium." (PMID 35962209, 2022). "In this respect, previous reports showed that increases in peripheral levels of C-reactive protein (CRP), interleukin-6 (IL-6), CXCL8 (IL-8), and tumor necrotic factor (TNF)-α are associated with the onset of post-operative delirium." (PMID 35641947, 2022).